CDC40 (cell division cycle 40)
Description:
Required for pre-mRNA splicing as component of the activated spliceosome. Plays an important role in embryonic brain development; this function does not require proline isomerization.
Synonyms: Ehb3; PRP17; PRPF17; FLJ10564; PCH15
Tractability: Small molecule: a structure with a bound ligand is known. PROTAC: ubiquitination databases record sites on it; its protein half-life has been measured.
Gene: Protein-coding gene on chromosome 6 (110,180,141 to 110,254,275, forward strand). Ensembl gene ENSG00000168438.
Subcellular location: Nucleus; Nucleus speckle
Subcellular location (Human Protein Atlas): Nucleoplasm
Pathways (Reactome):
Metabolism of RNA: Transport of Mature mRNA derived from an Intron-Containing Transcript; mRNA 3'-end processing; mRNA Polyadenylation; mRNA Splicing - Major Pathway
Disease: Dengue Virus-Host Interactions
Gene Ontology:
Molecular function: protein binding; RNA binding
Biological process: embryonic brain development; mRNA splicing, via spliceosome
Cellular component: catalytic step 2 spliceosome; nuclear speck; nucleoplasm; nucleus; post-mRNA release spliceosomal complex; post-spliceosomal complex; spliceosomal complex; U2-type catalytic step 1 spliceosome; U2-type catalytic step 2 spliceosome
Genetic constraint (gnomAD): Loss-of-function variants: 5 observed, 21.39 expected, observed/expected ratio (o/e) 0.23, 90% interval 0.12 to 0.49. The upper end of that interval is the gene's LOEUF score, 0.49, which puts it in group 2 of 6, group 1 being the genes least tolerant of losing a copy. Missense variants: 161 observed, 251.93 expected, observed/expected ratio (o/e) 0.64, 90% interval 0.56 to 0.73. Synonymous variants: 83 observed, 94.99 expected, observed/expected ratio (o/e) 0.87, 90% interval 0.73 to 1.05.
Homologues: Orthologues: chimpanzee CDC40 (100% identical), macaque CDC40 (99% identical), guinea pig Cdc40 (99% identical), mouse Cdc40 (99% identical), rat Cdc40 (99% identical), pig CDC40 (99% identical), dog CDC40 (98% identical), tropical clawed frog cdc40 (87% identical), zebrafish cdc40 (82% identical), Drosophila melanogaster CG6015 (61% identical), Caenorhabditis elegans prp-17 (51% identical), Caenorhabditis elegans Y54G2A.12 (20% identical). Paralogues in human: WDR25 (20% identical), WDR87 (16% identical).
Diseases named in the same sentence as CDC40 in open-access papers:
CDC40 is named in the same sentence as 10 diseases in open-access papers, as found by Europe PMC text mining. Sharing a sentence is not in itself a finding about the gene and the disease. The quoted sentences say what the papers report.
microcephaly (5 papers, 2022 to 2025). A congenital or acquired developmental disorder in which the circumference of the head is smaller than normal for the person's age and sex. "PCH15 is caused by homozygous mutation in the CDC40 gene and is a severe autosomal recessive neurodevelopmental disorder characterized by the congenital onset of progressive microcephaly and poor or absent psychomotor development with severely impaired intellectual development apparent from birth." (PMID 36076253, 2022).
colorectal cancer (2 papers, 2015 to 2016). A primary or metastatic malignant neoplasm that affects the colon or rectum. "MiR-139-5p promotes cell cycle arrest in G0/G1 phase by targeting NOTCH1 in colorectal cancer, and miR-378a-5p inhibits cell growth and the G1/S transition by targeting CDC40 in colorectal cancer." (PMID 26462034, 2015). "However, except for one report showing CDC40 as a target of miR-378 in colorectal cancer, the correlation between CDC40 and tumor malignancy has not been investigated." (PMID 27349221, 2016).
cancer (3 papers, 2016 to 2022). A tumor composed of atypical neoplastic, often pleomorphic cells that invade other tissues. "Finally we chose CDC40 as a candidate target of miR-1269b because it regulates cell cycle progress and its impact in cancer cells was unclear." (PMID 27349221, 2016). "Accordingly, miR-1269b can affect the progression of cancer by targeting downstream genes (METTL3, CDC40, SVEP1, and PTEN)." (PMID 35252180, 2022).
tumor (3 papers, 2016 to 2023). "miR-1269b can also be induced by HBx to up-regulate CDC40 in an NF-κB-dependent manner to promote tumor cell growth and migration." (PMID 35252180, 2022). "CDC40 is a splicing factor involved in cell cycle control, which can remove E-cadherin and enhance vimentin, thereby promoting tumor cell migration." (PMID 35252180, 2022). "Four SFs were not significantly different between matched normal and tumor samples (CDC40, HNRNPH1, HNRNPCL1, and HNRNPM)." (PMID 37531400, 2023).
CDC40 also shares sentences with these, for which no sentence is quoted: colon cancer (1 paper); developmental delay (1); hepatoma (1); Hydrocephalus (1); mandibulofacial dysostosis (1); mitochondrial disease (1).